ARID1A (AT-rich interaction domain 1A)
Diseases named in the same sentence as ARID1A in open-access papers (continued):
Sharing a sentence is not in itself a finding about the gene and the disease.
cancer (continued). "There could be several factors involved for such ambiguous prognostic role of ARID1A within the same cancer type." (PMID 36123603, 2022). "Thus, the inhibition of EZH2 using tazemetostat or GSK126 causes synthetic lethality in ARID1A-, SMARCA4-, SMARCB1-, PBRM1-deficient cancers." (PMID 36371186, 2022). "For example, ARID1A (AT-rich interaction domain 1A)-deficient cancer cells, of which enhanced SLC7A11 expression by ARID1A-mediated chromatin remodeling disappears, are more susceptible to inhibition of the antioxidant glutathione due to excessive amounts of ROS-triggered apoptosis." (PMID 35178349, 2022). "Apart from IFN pathways, in agreement with our findings, ARID1A mutation could also result in a higher level of PD-1, MSI, and T cell infiltration to promote cancer immunity and potentiating favorable ICB treatment response." (PMID 36281289, 2022). "In addition, ARID1A and MAST3 that were located within the branches of patient 14 are among the recurrently mutated cancer genes." (PMID 35379887, 2022). "It is also suggested that monocyte CD300e and cancer ARID1A gene in sub15-4 (2020) may also be candidate topics that continue to follow." (PMID 34811710, 2022). "ARID1A is a subunit of the SWI/SNF epigenetic regulator that is frequently altered in cancer." (PMID 35379887, 2022). "Thus, depletion of ARID1A can be therapeutically exploited by targeting downstream effects to improve cancer treatment‐related outcomes." (PMID 36420658, 2022). "One of the therapeutic strategies explored in ARID1A mutant cancers has been synthetic lethality." (PMID 35774123, 2022). "Elsewhere, ARID1A mutation was seen to be involved in Type-I–IFN–Response pathway and regulatory T cell to interact with EC development, partly accounting for its advantageous role in many kinds of cancer." (PMID 36281289, 2022). "Together, these findings suggest a model wherein CRCs with ARID1A mutations have a higher TMB, which leads to the recruitment of PD‐L1‐expressing immune cells (especially macrophages) to the invasive front, enabling the cancer cells to escape immune response." (PMID 34042312, 2022). "Protein kinases are exploitable vulnerabilities in SMARCA4- and ARID1A-mutant cancers." (PMID 33941852, 2021). "Although the molecules and pathways involved in GSH synthesis, such as xCT and GSH/GCLC, are closely related to ferroptosis, they reported here that the inhibition of GSH/GCLC in ARID1A-deficient cancer cells caused apoptosis by ROS, but not ferroptosis." (PMID 34502181, 2021).
cancer (continued). "This is consistent with the rarity of ARID1A missense mutations compared to nonsense mutations and frameshifts in other cancer types, suggesting that missense mutations are not selected for in general due to their lack of an effect on downstream processes." (PMID 33957863, 2021). "Although ARID1A mutations are highly prevalent in ovarian follicular carcinoma (50%) and ovarian endometrial carcinoma (30%), as well as in many other types of cancer, none are a drug target." (PMID 34502181, 2021). "It suggested that ARID1A has the function of modulating the immune phenotype of cancers." (PMID 34715776, 2021). "Liquid biopsy test reported actionable alterations in ARID1A gene, rearranged during transfection (RET) gene fusions, epidermal growth factor receptor (EGFR) gene R776H mutation, breast cancer (BRCA) genes 1/2, and cyclin-dependent kinase inhibitor 2A (CDKN2A) gene mutations." (PMID 33608032, 2021). "Other studies also pointed that cancer patients harboring ARID1A alterations could benefit from ICIs treatment." (PMID 34715776, 2021). "Inactivation of ARID1A might activate cell cycle progression, leading to an uncontrolled cellular proliferation in cancer cells." (PMID 34249744, 2021). "It was also reported that ARID1A expression is related to PDL1 levels in various cancers." (PMID 34924820, 2021). "Researchers had also focused on the role of ARID1A in cancer therapeutics." (PMID 34715776, 2021). "Downregulation of ARID1A and ARID1B, the variant subunits of the BRG1/BRM-associated factor complex from the SWI/SNF chromatin remodelling family, in various cancer cells might lead to deficiency in DNA repair." (PMID 35127746, 2021). "The incidence of ARID1A loss in GC ranged from 8% to 70% (median 25%) using various cutoff levels defined as cancer cells weak or without nuclear staining, or nuclear staining < 10%." (PMID 33481850, 2021). "However, in the present study of the intramucosal stage of EBVaGC, there were morphological differences between ARID1A-lost and -preserved carcinomas." (PMID 34469459, 2021). "Although no direct restoration of ARID1A is currently possible, loss of the tumour suppressor gene results in specific weak points in cancer cells that are suitable for therapy." (PMID 31906887, 2020). "However, ARID1A or ARID1B mutations and the resultant functional deficiencies were tightly associated with the sensitive phenotype for cancer immunotherapy." (PMID 32791957, 2020). "However, it has been reported that inactivating mutations in SWI/SNF subunits (ARID1A, PBRM1, SMARCB1, and SMARCA4) also sensitize cancer cells to T cell-mediated destruction." (PMID 32649682, 2020). "Hence, we performed this pan-cancer analysis to evaluate the prevalence and predictive value of ARID1A alterations across >40,000 cases in multiple cancer types." (PMID 31949479, 2020). "Additionally, our research is the first to investigate the role of ARID1B, which is another ARID1 subunit similar to ARID1A, in changing the phenotype of cancer." (PMID 32791957, 2020). "ARID1A, a SWI/SNF complex subunit, is frequently mutated in cancer." (PMID 33381446, 2020).
cancer (continued). "In this research, we confirmed the important role of ARID1A deficiency in elevating cancerous mutability and changing tumors to exhibit an aggressive phenotype in NSCLC, which was proposed by published works on other cancer types." (PMID 32791957, 2020). "Promising targets for potentially interesting inhibitors are the proteins of the JAK/STAT, Wnt/β-catenin, Hedgehog and Notch signalling pathways, inhibitors that target mutations in chromatin-remodelling genes, such as ARID1A, PBRM1, and BAP1, and inhibitors of cancer-associated fibroblasts." (PMID 32423017, 2020). "Our study contributes molecular clues by indicating that this is not linked to CTNNB1/ARID1A mutations, but more likely attributed to the hypoxia frequently found in cancers." (PMID 33084574, 2020). "We macrodissected cancer cells, extracted DNA, and performed Sanger sequencing for ARID1A." (PMID 32868822, 2020). "We also observed significantly more mutations of PIK3CA [frequently found in microsatellite unstable (MSI) GCs] and ARID1A (associated with MSI along with hypermutations and PD-L1 expression in cancers including GC) in the INT subtype compared to the COD subtype." (PMID 31773340, 2020). "In addition, we found two relatively common cancer genes in more than one rare cancer case: ARID1A (occurred in two cases and twice in one case) and CDKN2A (occurred in two cases)." (PMID 32570879, 2020). "As a result, ARID1A deficiency may lead to impaired MMR and thus correlates with the MSI genomic feature of cancer." (PMID 31277418, 2019). "Indeed, compared with ARID1A wild-type tumors, ARID1A-mutated tumors displayed significantly less genomic instability as measured by CNA in all tested cancer types." (PMID 31492885, 2019). "ARID1A mutant cancer cells often require the function of its paralog ARID1B." (PMID 31123059, 2019). "ARID1A is thus a likely target for personalized medicine in cancer treatment." (PMID 31581674, 2019). "Consequently, ARID1A has been proposed as a promising therapeutic target to sensitize cancer cells to chemotherapy and radiation." (PMID 31847141, 2019). "Lymphatic invasion and venous invasion were significantly associated with negative ARID1A expression, suggesting that ARID1A plays a role in cancer progression." (PMID 31043675, 2019). "Therefore, our results suggest that ARID1A is required for maintaining the expression of cancer-relevant downstream targets of the MEK/ERK pathway in KRAS-mutated CRC cells." (PMID 31217031, 2019). "This has important implications for human cancers, which exhibit a broad spectrum of Arid1a levels." (PMID 30014851, 2018). "Loss of ARID1B in an ARID1A-deficient background eliminates the intact SWI/SNF complex, indicating that ARID1B is essential for the formation or stabilization of an intact SWI/SNF complex and, thus, the survival of ARID1A-mutant cancer cell lines." (PMID 29890703, 2018). "However, loss of ARID1A, along with low-level HNF-1b expression, was common in patients with cancer recurrence and was correlated with late-stage and worse survival outcome." (PMID 29743986, 2018).
cancer (continued). "Currently, we have no indications that ARID1A loss sensitizes other cancer types to BET inhibition, suggesting an OCCC-specific context dependency for the findings we report here." (PMID 29760405, 2018). "It has been stated previously that ARID1B may be a potential therapeutic target for ARID1A mutant cancers." (PMID 29760405, 2018). "Specifically, Arid1a/Arid 2a is mutated in approximately 25% of cancers regardless of HCCs regardless of etiology." (PMID 29771950, 2018). "We also found a significant correlation between the loss of ARID1A immunoreactivity and reduced ARID1B levels, suggesting that ARID1B could be a target for anti-cancer therapy." (PMID 29890703, 2018). "It has been reported that inhibition of the methyltransferase EZH2 may represent a novel treatment strategy for ARID1A mutant cancers." (PMID 29760405, 2018). "While observing increased median ARID1A protein levels in all carcinoma subgroups compared to normal urothelial controls (n = 21), the percentage of cases showing ARID1A protein loss was positively correlated with increasing stage and grade culminating in a rate of 14.1% in muscle-invasive disease." (PMID 30138427, 2018). "The reason for the selectivity for ARID1A mutations in cancer is not understood, and the functional basis for the synthetic lethal relationship between ARID1A and ARID1B has not yet been determined." (PMID 28967863, 2017). "ARID1A, a subunit of the SWI/SNF chromatin remodeling complex, is frequently mutated in cancer." (PMID 28967863, 2017). "Interestingly, compared to ARID1A, mutations in ARID1B and ARID2 are rare in cancer, apart from in neuroblastoma and hepatocellular carcinoma." (PMID 28967863, 2017). "In this study, we aimed to identify drugs sensitivities in ARID1A-mutant cancer cell lines." (PMID 27486766, 2016). "Our data suggest that ATRi could have potential as single-agent treatments for ARID1A defective cancers." (PMID 27958275, 2016). "Cutoff levels for ARID1A deficiency was defined as cancer cells weak or without nuclear staining, or nuclear staining <10%." (PMID 27354232, 2016). "Interestingly, we found that elesclomol, which potently induces ROS formation by disrupting the electron transport chain in the mitochondria, exhibited the greatest difference in sensitivity between the ARID1A-mutant and ARID1A-wildtype cancer cell lines." (PMID 27486766, 2016). "Thus both PIK3CA and PDK1, as well as p-AKT, were potential drug targets in ARID1A-mutant cancer cells." (PMID 27323812, 2016). "Although the upregulation of p-AKT in cancer cells by ARID1A deficiency has been observed, no direct link was established between ARID1A, a transcriptional regulator, and PI3K/AKT pathway, a typical pathway by phosphorylation cascade." (PMID 27323812, 2016). "Participants with ARID1A− and ARID1A+, had a low stage of cancer according to FIGO (International Federation of Gynecology and Obstetrics) in 66.1% and 87.0% of cases (p = 0.26), with the corresponding figures being 53.1% and 63.6% (p = 0.002) using the TNM classification." (PMID 26384299, 2015). "Like most human cancers, nonsense and frame shift mutations throughout ARID1A gene have frequently been found in HCC, indicating that these ARID1A mutations could inactivate ARID1A function in HCC." (PMID 26569409, 2015). "Eligible were prospective studies reporting data on prognostic parameters in subjects with cancer, comparing participants with presence of ARID1A (ARID1A+) vs. ARID1A−, assessed either via immunohistochemistry (loss of expression) or with genetic testing (presence of mutation)." (PMID 26384299, 2015). "For all-cause mortality and cancer recurrence, only differences in percentage of low-grade cancers between ARID1A− vs. ARID1A+, country, and number of adjustments were significant moderators, while for adjusted hazard ratios no significant moderators were evident." (PMID 26384299, 2015).
cancer (continued). "The study showed that ARID1A is mutated in over 50 % of ovarian CCCs and pharmacological inhibition of enhancer of zeste homolog 2 (EZH2) represents a novel treatment strategy for cancers involving ARID1A mutations." (PMID 26675567, 2015). "Furthermore, somatic mutations located within the functional domains have been identified to be predictive of an inactivate ARID1A, confirming earlier reports of the low levels of ARID1A gene expression reported in other cancers." (PMID 24955791, 2014). "Thus, a recent study demonstrated a synthetic lethal relationship between inactivating mutations of the homologs ARID1A and ARID1B, both in primary and cancer cells." (PMID 24979463, 2014). "However, studies have also indicated that double deletion of ARID1A and ARID1B can trigger rapid carcinogenesis in the liver and skin of mice, suggesting caution should be exercised when employing homologous therapy for treating cancers with mutated ARID1." (PMID 39779467, 2025). "Given the potential synthetic lethality relationship between ARID1A and EZH2 in cancer cells, the current evidence suggests that EZH2 could be a new target for synthetic lethality that can be targeted with drugs in cancers with ARID1A deficiency, as confirmed in this study." (PMID 39773749, 2025). "Notably, ARID1A, which is frequently mutated in cancer, was not identified as a determinant for chromosomal instability, and consistently, we find no impact of ARID1A on centromere fragility in our assays." (PMID 40011561, 2025). "Importantly, this subtype of PC may be targetable through exploiting their defective DNA-damage response as has been demonstrated in other ARID1A-mutant cancers." (PMID 39885328, 2025). "Broad ETC inhibition may not be effective for ARID1A-deficient cancers, but targeting specific subunits tied to altered metabolic dependencies may offer a more precise therapeutic strategy." (PMID 40564930, 2025). "Loss of the frequently mutated chromatin remodeler ARID1A, a subunit of the SWI/SNF cBAF complex, results in less open chromatin, alternative splicing, and the failure to stop cells from progressing through the cell cycle after DNA damage in bladder (cancer) cells." (PMID 40170512, 2025). "There were 6 samples with missense mutations, and the remaining samples did not have any variants in ARID1A but still resulted in no ARID1A protein expression, indicating that epigenetic mechanisms are important to consider as driver mechanisms of cancer progression." (PMID 40429787, 2025). "When the mismatch repair function in the cancer cell is not working properly due to a lack of the ARID1A gene, any mutation that occurs may create a neoantigen on the surface of the cancer cell that can confer immune cell recognition." (PMID 40429787, 2025). "Therefore, whether ARID1A serves as a useful biomarker for predicting a patient’s response to ICI therapy may vary according to cancer type." (PMID 38893118, 2024). "However, ARID1A is predominantly reported to inhibit EMT in a cancer context." (PMID 39226899, 2024). "Furthermore, ARID1A-positive cancers exhibited a longer disease-free and overall survival." (PMID 36890819, 2023). "Additionally, ARID1A loss may also interfere with the immune checkpoint, promoting MLH1 silencing and upregulation of PD-L1 (programmed death ligand 1), leading to cancer cells escaping from immune checkpoint surveillance." (PMID 38203635, 2023).